CRX (cone-rod homeobox)
Diseases named in the same sentence as CRX in open-access papers (continued):
Sharing a sentence is not in itself a finding about the gene and the disease.
retinopathy (17 papers, 2009 to 2026). "Most CRX-associated retinopathies are presumed to be inherited in an autosomal dominant fashion due to gain-of-function and dominant negative effects of the mutated protein." (PMID 41595470, 2026). "Given the tremendous genotypic and phenotypic variability, continued description of CRX-associated retinopathies is required for complete characterization of the range of possible genotype–phenotype combinations." (PMID 41595470, 2026). "A second patient was excluded because their pedigree demonstrated a likely X-linked inheritance pattern, which is inconsistent with CRX-associated retinopathies." (PMID 41595470, 2026). "Dominant CRX-associated retinopathy exhibits considerable phenotypic variability, even within families sharing the same mutant CRX allele." (PMID 39632990, 2025). "CRX-linked retinopathies vary greatly in the age of onset, rate of progression, and severity, reflecting the complexity of CRX’s mechanisms of action and highlighting challenges in evaluating sequence variants in different genetic backgrounds." (PMID 38414750, 2024). "The use of animal models also helps to dissect the disease progression for cell-type specificity, expanding the scope of genotype–phenotype relationship; such examples can be found in CRX-associated retinopathies." (PMID 37181651, 2023). "Here, we use Cone-Rod Homeobox (CRX) as a model to decipher the disease-causing mechanisms of two HD mutations, p.E80A and p.K88N, that produce severe dominant retinopathies." (PMID 37963072, 2023). "Mutations in the cone-rod-homeobox protein CRX are typically associated with dominant blinding retinopathies with variable age of onset and severity." (PMID 26324254, 2015). "The molecular functions of several CRX mutations associated with human retinopathy have been investigated in vitro and in vivo in Drosophila." (PMID 24516401, 2014). "Given the scarcity of published literature on CRX-associated phenotypes, we conducted a case series review of patients with CRX-associated retinopathy at the Bascom Palmer Eye Institute to assess the frequency of nasal retinal degeneration and potential genotype–phenotype correlations." (PMID 41595470, 2026). "This study suggests that the combination of actomyosin tension-modulating drugs with CRX augmentation may provide a more precise and effective treatment for CRX-associated retinopathies in human." (PMID 38049871, 2023). "Our results implicate a threshold effect of gene expression level on photoreceptor function and survival, highlight the importance of CRX in photoreceptor subtype development and maintenance, and provide a molecular basis for phenotype variability in CRX-associated retinopathies." (PMID 26324254, 2015). "These genes also affect the timing of sleep, for example, mutations in human CRX and AIPL1 were shown to cause inherited retinopathy and the associated symptoms of severe sleep abnormalities or insomnia." (PMID 40101169, 2025). "NRL, CRX, and NR2E3 are key transcription factors that regulate photoreceptor differentiation, and mutations in these lead to retinopathies." (PMID 19898638, 2009). "Mutations are widely scattered in different domains; no unified conclusion can correlate the severity of CRX-associated retinopathies with the mutation spectrum." (PMID 38049871, 2023). "Building on that observation, we tested the hypothesis that overexpression of a correct CRX cDNA increasing the ratio of normal to mutant protein (gene augmentation) may rescue defects in dominant human CRX retinopathies." (PMID 33513359, 2021). "Also, RP1L1, PROM1, CRX, CFI and CFB, and KCNJ13 have been linked to retinopathy." (PMID 33330132, 2020).
tumor (14 papers, 2009 to 2026). "A specific example of the practical diagnostic use of CRX immunohistochemistry can be provided by a recent case evaluated at Children's Hospital, Boston of a high-grade neoplasm of the pineal region." (PMID 19936203, 2009). "Consistent with impaired photoreceptor differentiation observed in MYCN-driven tumors, CRX expression was undetectable within these tumor tissues." (PMID 40943594, 2025). "Among the identified RB tumor marker genes are known RB markers like the immature precursor gene CRX as well as genes of mature photoreceptors including phosphodiesterase 6H (PDE6AH) and arrestin 3 (ARR3), specific for cones." (PMID 39695086, 2024). "Hematoxylin and eosin as well as luciferase stains revealed RB tumor development, while CRX positivity proved their RB tumor cell origin and Ki67 staining verified a positive proliferation status of the tumor." (PMID 38217258, 2024). "In order to analyze RB tumors grown in vivo histologically, enucleated rat eyes were embedded in paraffin, cut and immunohistologically stained for CRX and Ki67 to verify the RB origin and proliferation potential of the tumor xenografts." (PMID 38217258, 2024). "After 4 weeks of RB tumor growth, we enucleated the rats eyes of all three treatment regimen and performed histological stainings for Ki67, CRX, and luciferase to verify the RB origin and the proliferation potential of the tumor xenografts." (PMID 38217258, 2024). "The corresponding CRX staining confirmed the RB nature of the tumors and Ki67 staining the proliferation activity of the tumor cells." (PMID 35158945, 2022). "Cells from clusters 1 and 4 (CRX+/ARR3+/GUCA1C+ tumor cells) corresponded to the last two profiles (10q gain ± 2p gain)." (PMID 34552068, 2021). "The CRX+/EBF3+/GAP43+ tumor population (clusters 0 and 2), presenting numerous genomic alterations, appeared to be genomically homogeneous." (PMID 34552068, 2021). "The CRX+/ARR3+/GUCA1C+ tumor population (clusters 1 and 4) was less unstable and consisted of two genomically different subpopulations." (PMID 34552068, 2021). "All cells from clusters 0 and 2 (CRX+/EBF3+/GAP43+ tumor cells), and some cluster 3 cells, corresponded to the first profile (multiple alterations)." (PMID 34552068, 2021). "Other candidate markers of this set of patient's serum are apoptosis regulator like MTEFD1 and TSPO2 as well as a transcription factor, CRX whose expression and function is essential for growth of tumor cells with photoreceptor differentiation." (PMID 25437182, 2014). "To investigate the specificity of CRX in the diagnosis of tumors of pineal/retinal lineage, we performed immunohistochemistry for CRX on a number of tumor types that frequently enter the differential diagnosis of pineal masses." (PMID 19936203, 2009). "Moreover, another study has reported CRX and NRL as another two SE-associated subtype-specific tumor-dependent TFs." (PMID 36273157, 2022). "RB170 tumor cells had cone properties, as shown by CRX and ARR3 expression." (PMID 33270844, 2020). "The heterogeneity of CRX staining in a portion of the tumor samples may reflect biological heterogeneity within these tumors." (PMID 19936203, 2009). "Therefore, it would be interesting to test in future whether ARL4D also works as an essential gene and is transcriptionally regulated by OTX2 and CRX as well in ARL4D-high G4-MB tumors if proper tumor models are available." (PMID 36273157, 2022). "Like GP3-C2, GP4-C2, the photoreceptor differentiated tumor cell cluster of G4-MB, exhibits the highest expression of ARL4D and highly expresses OTX2 and CRX." (PMID 36273157, 2022).
tumor (continued). "Immunohistochemical analysis of this tumor showed a mutually exclusive expression of ARR3 and EBF3, defining two types of areas (CRX+/ARR3+/EBF3− and CRX+/ARR3−/EBF3+), as observed in about 30% of subtype 2 tumors." (PMID 34552068, 2021). "Moreover, our scRNA-seq data analysis also revealed ARL4D, OTX2 and CRX were all enriched in GP3-C2, the photoreceptor differentiated tumor cell cluster of G3-MB defined in a recent single-cell transcriptomic study of MB." (PMID 36273157, 2022). "Moreover, the tumor cell subpopulations expressing the highest level of PSMB5 (GP3-B1) are different from the ones of MYC, OTX2 or CRX (GP3-B2 for MYC, GP3-C2 for OTX2 and CRX), further supporting the involvement of unidentified SE-associated TFs in regulating PSMB5 transcription in G3-MB." (PMID 36273157, 2022). "The co-expression of CRX/EBF3/GAP43 (early photoreceptor/cone marker and neuronal/ganglion cell markers) was unique to tumor cells as it was absent or very rare during normal retinal development." (PMID 34552068, 2021).
cancer (5 papers, 2009 to 2025). A tumor composed of atypical neoplastic, often pleomorphic cells that invade other tissues. "During retinal development, OTX2 occupies a pivotal position in a photoreceptor gene hierarchy, including basic leucine zipper TFs NRL and CRX, both overexpressed in G3 MB, where they promote cancer survival via the anti-apoptotic factor BCL2L1." (PMID 41198629, 2025). "In conclusion, we have developed a versatile, molecularly well-defined, peptide-based vaccine system which incorporates the potent TLR4 ligand, CRX-527, in peptide-adjuvant conjugates for cancer vaccination." (PMID 35739113, 2022). "Functional studies of CRX in these cancers would certainly seem warranted, given the known dependency of retinal and pineal lineage cells on this factor in humans and mice." (PMID 19936203, 2009). "Gene expression profiling analysis of a wide range of human cancers and cancer cell lines also supports that CRX RNA is highly lineage restricted in cancer." (PMID 19936203, 2009). "OTX2 and other photoreceptor TFs, including NRL and CRX, drives anti-apoptotic factors like BCL2L1, linking this gene program to sustained cancer cell viability." (PMID 41198629, 2025). "Both the Rb subtypes expressed the cone-specific markers RXR γ, CRX, OTX1, and TRβ2 (data not shown), compared to the pediatric retina, supporting the cone photoreceptor origin of cancer." (PMID 35626705, 2022).
infection (2 papers, 2021 to 2024). The state of being infected such as from the introduction of a foreign agent such as serum, vaccine, antigenic substance or organism. "By using the human CRX promoter, a AAV2-CRX vector can precisely target a distinct apical lamina of the photoreceptor layer in the RO and function properly after infection." (PMID 34719743, 2021).
autosomal dominant disease (1 paper, 2021). Autosomal dominant form of disease. "For truncations in CRX and RHO, loss-of-function mutations are responsible for autosomal recessive diseases while dominant-negative mutations lead to autosomal dominant diseases." (PMID 33681214, 2021).
genetic diseases (1 paper, 2021). "This method could theoretically be applied to any dominant CRX mutation, and could work for additional dominant genetic diseases in other tissues, providing a broader application outside the specific mutations presented in this work." (PMID 34653402, 2021).
CRX also shares sentences with these, for which no sentence is quoted: Ciliopathies (3 papers); Leber congenital amaurosis 7 (2); Stargardt disease (2); age-related macular degeneration (1); autosomal recessive disease (1); autosomal recessive retinitis pigmentosa (1); Bardet-Biedl syndrome (1); benign concentric annular macular dystrophy (1); Cerebellar atrophy (1); Coffin-Siris syndrome 12 (1); glioblastoma (1); macular coloboma (1); night blindness (1); Nystagmus (1); occult macular dystrophy (1); pigmented paravenous retinochoroidal atrophy (1); pineocytoma (1); retinal tumors (1); Usher syndrome (1).